ATIC (5-aminoimidazole-4-carboxamide ribonucleotide formyltransferase/IMP cyclohydrolase)
Diseases named in the same sentence as ATIC in open-access papers (continued):
Sharing a sentence is not in itself a finding about the gene and the disease.
cancer (continued). "Hence, these results imply that ATIC may be involved in tumorigenesis and may influence the survival of cancer cells." (PMID 34650911, 2021). "For human carcinomas, inhibition of aminoimidazole carboxamide ribonucleotide transformylase (ATIC), which catalyzes the last two steps of de novo purine biosynthesis and decreases cell proliferation and cell cycle progression, highlighting a potential role for ATIC inhibitors in cancer therapy." (PMID 32218208, 2020). "Thus the anti-ATIC strategy may effectively inhibit cancer growth yet with minimal toxicity to normal cells." (PMID 29246230, 2017). "In the Cancer Cell Line Encyclopedia (CCLE) database, ATIC was found to be overexpressed, while CDKN1A, DNAJB9, EDEM1, and GABARAPL1 exhibited lower expression levels, aligning with the gene expression patterns observed in our model equations." (PMID 41040512, 2025). "In addition, 5-aminoimidazole-4-carboxamide ribonucleotide formyltransferase/IMP cyclohydrolase (ATIC) acts as an enzyme catalyzing the last two reactions in the purine biosynthetic pathway and has an important regulatory effect on the progression and development of cancers." (PMID 40442541, 2025). "However, the specific role of the ATIC gene in modulating cancer progression remains unknown." (PMID 35205374, 2022). "Both ATIC and BZW2 are considered human oncogenic genes that promote cancer proliferation and migration through mTOR signaling." (PMID 32559205, 2020). "Additionally, we tested anti-ATIC-autoantibody biomarker and conventional biomarker AFP simultaneously in the patient’s sera and suggested that the combinational measurement of two biomarkers generated by different mechanisms can enhance the diagnostic accuracy in cancer." (PMID 33352757, 2020). "Among them, four genes (PPAT, ATIC, IMPDH1, and RRM2) belong to the purine de novo biosynthesis pathway which is indispensable for cancer cell proliferation." (PMID 33520699, 2020). "However, whether and how ATIC modulates progression of cancer remains largely unknown." (PMID 29246230, 2017). "Three enzymes (MTHFD2, ATIC, and SHMT2) in this pathway were found to be overexpressed in many cancers." (PMID 25243088, 2014). "Furthermore, we identified NADBPs that are known (ATIC, AR and IDH2),as well as potential new drug targets in cancer (FH and NT5C2)." (PMID 36880517, 2023). "PFK-2/FBPase-2, ATIC, LTA4H and Jmjd6 are four multifunctional enzymes with a proven relevant role in the proliferation and/or survival of cancer cells, and their inhibition can increase the life expectancy of some cancer patients." (PMID 35056904, 2021). "Despite these elegant observations, the significance of ATIC in human cancer has not been fully investigated." (PMID 29246230, 2017). "Inhibition of IMPDH by mycophenolic acid (the active form of mycophenolate mofetil) increased ZMP levels in cancer cells, suggesting that inhibitors of GMP and/or AMP synthesis suppress ZMP clearance and facilitate AMPK activation, mimicking the inhibition of ATIC by methotrexate." (PMID 40793247, 2025).
neurodevelopmental disorder (2 papers, 2020 to 2023). A behavioral and cognitive disorder with onset during the developmental period that involves impaired or aberrant development of intellectual, motor, or social functions. "Among them, only two genes (ADSL and ATIC) were associated with neurodevelopmental disorders." (PMID 32384607, 2020). "Previous studies related to neurodevelopmental disorders have shown reduced concentrations or deficiencies of ADA and ATIC, while very few cases of elevated expression levels have been reported." (PMID 36818658, 2023).
ATIC also shares sentences with these, for which no sentence is quoted: infection (8 papers); lung adenocarcinoma (4); acute lymphoblastic leukemia (2); autoimmune disease (2); bladder (2); inflammatory myofibroblastic tumor (2); multiple myeloma (2); abscess (1); adenocarcinoma (1); adenoma (1); anemia (1); bladder cancer (1); Cirrhosis (1); congenital blindness (1); esophageal squamous cell carcinoma (1); gastric cancer (1); gout (1); head and neck cancer (1); heart failure (1); hyperhomocysteinemia (1); Hypertension (1); Hypoglycemia (1); inflammatory bowel disease (1); Intellectual disability (1); leukemia (1); liver diseases (1); nasopharyngeal carcinoma (1); neurodegenerative disease (1); optical atrophy (1); pediatric osteosarcoma (1).
A further 4 diseases each share a sentence with ATIC in 1 paper.